FGF23 (fibroblast growth factor 23)
Diseases named in the same sentence as FGF23 in open-access papers (continued):
Sharing a sentence is not in itself a finding about the gene and the disease.
Obesity (continued). "Another factor contributing to calcium-phosphate dysregulation in obesity is fibroblast growth factor 23 (FGF-23), a hormone that is elevated in metabolic disorders." (PMID 40136609, 2025). "We used a murine model of HFD-induced obesity and examined FGF23 expression levels and protein localization in the stomachs." (PMID 40483378, 2025). "While in normal-weight subjects, endothelial cells of single blood vessels were weakly FGF23-immunoreactive, FGF23 staining of interconnected blood vessels was more pronounced in patients with obesity indicating a higher vascularization." (PMID 40483378, 2025). "Gastric FGF23 was also detectable in patients with obesity, mainly in endothelial cells of dilated and interconnected vessels." (PMID 40483378, 2025). "In summary, we show that HFD-fed mice and patients with obesity exhibit FGF23-expressing cells in altered gastric areas." (PMID 40483378, 2025). "The study further implicates FGF23 in broader metabolic disturbances, possibly linking it to the obesity commonly observed in XLH patients." (PMID 39329699, 2024). "One study has observed elevated serum levels of FGF23 in individuals with obesity, especially those with abdominal obesity." (PMID 38732094, 2024). "In this context, studies including pre- and post-menopause women and adult men showed that circulating FGF23 was significantly higher in individuals with obesity, compared to lean individuals." (PMID 36831188, 2023). "It is also the first study that demonstrates the association of FGF-23, osteopontin, NGAL and sclerostin concentrations with obesity, cardiovascular risk factors, glucose homeostasis and BMR following a 1-year life-style intervention program." (PMID 36145151, 2022). "In humans, clinical studies support a potential role of FGF23 signalling in the metabolic status of individuals, including insulin resistance, dyslipidemia, and obesity." (PMID 34551713, 2021). "Our results also revealed that obesity modulated the response of omentin-1 and FGF-23 to the different macronutrients." (PMID 31652917, 2019). "The postprandial reductions of omentin-1 and FGF-23 after glucose and protein loads were influenced by obesity." (PMID 31652917, 2019). "Omentin-1 and FGF-23 levels showed significant interactions between obesity and macronutrients because obesity influenced postprandial levels differently during the oral glucose and protein challenges." (PMID 31652917, 2019). "Leptin, which is increased in rats that are fed high levels of fat, even before the development of obesity, has been shown to stimulate FGF23 secretion by osteocytes." (PMID 30513703, 2018). "Leptin, an adipokine that has a profound influence on the regulation of energy intake and that is consistently increased in obesity, has been shown to regulate the synthesis and secretion of FGF23, a major phosphaturic hormone." (PMID 30322116, 2018). "The endocrines FGF19, FGF21, and FGF23, have great potential to be important therapeutics for a variety of human diseases such as obesity, type II diabetes, and kidney and cardiovascular diseases." (PMID 30068552, 2018). "Role of Hormonal and Genetic Mediators: The FGF23‐Klotho axis, influenced by mineral metabolism (notably phosphate and vitamin D), may be perturbed in obesity." (PMID 40678338, 2025). "It is intriguing to speculate that gastric FGF23 may contribute to the elevated FGF23 levels, at least in patients with severe obesity." (PMID 40483378, 2025). "Higher densities of FGF23-expressing cells in HFD-fed mice and in patients with obesity could point to a local demand for FGF23 production in the changing gastric epithelium." (PMID 40483378, 2025). "Since anti-FGF23 therapy is, however, already available for patients, further studies are warranted to elucidate whether such therapy is beneficial in obesity." (PMID 40483378, 2025).
Obesity (continued). "Since leptin is elevated in the stomach of mice in response to a HFD and in patients with obesity, it appears to be possible that enhanced gastric leptin might contribute to gastric FGF23 production." (PMID 40483378, 2025). "Chemerin‐dependent FGF23 regulation may particularly play a role in states of enhanced chemerin production, i.e. obesity." (PMID 39887469, 2025). "Moreover, insulin resistance, mediated partly by UnOC and FGF23 (bone hormones) alterations in subjects with obesity, contributes to the osteoporosis scenario in obesity." (PMID 36831188, 2023). "Overall, whether FGF23 is an important putative factor in bone health in PCOS, especially in women with obesity where FGF23 levels are higher, remains to be determined." (PMID 37251667, 2023). "However, the data from existing research on serum FGF23 levels in children with obesity are inconsistent." (PMID 35769079, 2022). "Therefore, the increase in Klotho levels accompanied by a decrease in FGF23 induced by AT seems to be an important therapeutic target for renal damage attenuation inherent to obesity conditions." (PMID 34621463, 2021). "These include inflammation, preexisting CKD or coronary heart disease, obesity, and high leptin levels, and all of them may have a further impact on FGF23 secretion." (PMID 34208131, 2021). "FGF-23 is elevated in conditions of insulin resistance and obesity." (PMID 27391040, 2016). "There are also strong correlations with FGF23, obesity and insulin resistance." (PMID 24839967, 2014). "It is tempting to speculate that the mechanical shear stress and loading of obesity interact with the relative hypoxia of low iron stores on bone to secrete FGF-23." (PMID 23555610, 2013). "Moreover, it has to be kept in mind that comorbidities such as T2DM are common in subjects with obesity and that these may also impact FGF23 production." (PMID 40483378, 2025). "Moreover, we studied FGF23 in gastric specimens from patients with obesity." (PMID 40483378, 2025). "Notably, the induction of ER stress by FGF23 may play a role in the severe obesity observed in patients with XLH, suggesting FGF23 as a potential trigger for metabolic dysregulation and increased fat accumulation." (PMID 39329699, 2024). "No genetic association of ASD with FGF23 was found after correction for obesity and BMI." (PMID 37764834, 2023). "Moreover, high content of fat and obesity may stimulate systemic inflammation and renal injury which could also affect FGF23." (PMID 34208727, 2021). "In addition, feeding high fat and obesity may elicit systemic inflammation and renal injury which could also influence FGF23." (PMID 29856857, 2018). "In addition, high fat feeding and obesity may elicit systemic inflammation and renal injury which could also influence FGF23." (PMID 30513703, 2018). "Our previous studies reported significant positive correlations between both serum FGF23 and NGAL levels and obesity, whereas serum OCN levels were significantly inversely correlated with obesity." (PMID 30424752, 2018). "Through paracrine actions, FGF23 may be involved in regulating HFD-induced and obesity-related gastric pathophysiological processes." (PMID 40483378, 2025). "Serum BAP and FGF23 levels were not different between the control group and the overweight/obesity group in both genders (p>0.05)." (PMID 35769079, 2022). "The ingestion of a high calorie/high-fat diet has been also shown to increase plasma concentrations of FGF23 and the effect was independent of obesity." (PMID 34208727, 2021). "Subjects with overweight/obesity had significantly lower serum osteocalcin levels and higher serum FGF23 levels than subjects without these conditions (P < 0.001)." (PMID 30424752, 2018). "Therefore, the relevant effects of serum OCN, FGF23 and NGAL levels on obesity must be further confirmed in large-scale prospective studies and mechanistic studies." (PMID 30424752, 2018).
Obesity (continued). "Our study did not reveal whether enhanced gastric FGF23 production in obesity drives pathophysiological processes or which role it has." (PMID 40483378, 2025). "The relationship between obesity and FGF23 levels is not completely clarified." (PMID 38732094, 2024). "This lack of an effect on obesity could well reflect the reduced hepatic 25-hydroxylaton of vitamin D and the increased secretion of FGF-23 secretion seen in obesity—the latter reducing activity of the vitamin D-activating 1-alpha hydroxylase and thus reducing calcitriol formation." (PMID 37189612, 2023). "Obesity may promote FGF-23 production in the absence of chronic kidney disease." (PMID 37660205, 2023). "CDCP1, FGF23, HGF and IL-6 still had more prominent positive associations with %BF in overweight compared to normal weight subjects and the coefficients did not indicate that the associations were driven by obesity, whereas MCP-1 had a clear positive association with %BF only in the obese group." (PMID 34059769, 2021). "Thus, in these studies, the effect of a high fat diet on FGF23 seems to be independent of obesity." (PMID 30513703, 2018).
Hypercalcemia (63 papers, 2012 to 2026). An abnormally increased calcium concentration in the blood. "Low dietary phosphate can also cause hypercalcaemia, due to suppression of FGF23 or elevations in 1,25(OH)2D3." (PMID 33990852, 2022). "Hypercalcemia is implicated in vascular and valvular calcification, and elevated serum FGF23 is a clear marker for increased cardiovascular and overall mortality." (PMID 31615041, 2019). "Inhibition of FGF23 may theoretically cause an uncontrolled elevation in 1,25(OH)2D levels, increasing intestinal calcium absorption, leading to hypercalcemia, HC and NC." (PMID 39687707, 2024). "Alternatively, a bimodal association of serum calcium and FGF23 may be speculated, where both hypo- and hypercalcemia may be associated with low FGF23 production." (PMID 31615041, 2019). "FGF23-independent hypophosphatemic osteomalacia has low FGF23 levels and usually presents with high or normal 1,25(OH)2D3 levels and hypercalcemia." (PMID 41445556, 2025). "This direct VDR activation, however, increases the risks of hypercalcemia, accelerated catabolism, and the induction of FGF23 (a topic central to Paradigm Shift 3)." (PMID 41515987, 2025). "Several findings suggest that part of the phenotype is independent from PTH, namely hypercalcemia, and higher FGF23 (both intact and C-terminal fragment)." (PMID 38386045, 2024). "Steroids, particularly in high doses during the initial post-transplant period, can lead to hypercalcemia by inducing enzymes involved in vitamin D metabolism, which increases both parathyroid hormone and fibroblast growth factor 23 levels." (PMID 39064308, 2024). "Magnesium‐enriched PRD is a novel therapeutic strategy for managing feline CKD‐MBD in cats, further stabilizing plasma FGF23 and preventing hypercalcemia." (PMID 38952053, 2024). "Klotho-deficient mice exhibited mineral metabolism disorders, including phosphate retention, hypercalcemia; VC, valve calcification; and elevated fibroblastic growth factor-23 (FGF23) levels." (PMID 36210812, 2022). "In our in vivo model, we found that, in animals with constant levels of PTH, hypercalcemia induced a higher increase in FGF23 levels when vitamin D signaling was intact." (PMID 35807756, 2022). "Heterozygous (Ap2s1+/L15) mice were viable, and had marked hypercalcaemia, hypermagnesaemia, hypophosphataemia, and increases in alkaline phosphatase activity and fibroblast growth factor-23." (PMID 33729479, 2021). "Finally, we could not completely deny the possibility that unmeasured and residual confounding factors, including serum FGF23 levels, might have biased the observed association between hypercalcemia and increased risk of infection-related and all-cause mortality." (PMID 32286455, 2020). "A principal role of FGF23 in the regulation of 1α-hydroxylase has been demonstrated in Klotho and FGF23 hypomorphic mice, these have an inappropriately high 1α-hydroxylase expression, despite hypercalcemia and suppressed PTH." (PMID 33233840, 2020). "Laboratory data showed hypercalcemia with a normal serum phosphate level and high serum 1,25-hydroxyvitamin D3, fibroblast growth factor 23 (FGF23) and calciprotein particle (CPP) levels." (PMID 33564447, 2019). "In single Fgf23 and Klotho knockout mice, the calcium-conserving function of FGF23 is masked by the profound upregulation of 1,25(OH)2D3 production and subsequent hypercalcemia." (PMID 29892265, 2018). "Therefore, increased serum FGF23 levels are expected to stimulate renal calcium reabsorption and further exacerbate hypercalcemia in our Gna11-KO mice." (PMID 38530370, 2024). "FGF23 also interacts with serum PTH, although the association is less clear and may be based on hypercalcemia." (PMID 31615041, 2019). "Thus, hypercalcemia may account for the elevated serum iFGF23 and skeletal Fgf23 mRNA levels observed in Gna11+/– mice." (PMID 38530370, 2024).
Hypercalcemia (continued). "However, data in humans suggest that only long-term hypercalcemia might affect FGF23 secretion, since an acute increase of blood Ca levels was not accompanied by an increase in FGF23 concentrations." (PMID 26870965, 2016). "While FGF23 represses CYP27B1 and activates catabolism of active hormone, increased PTHLH secretion can lead to hypercalcemia via inactivation of VDR." (PMID 37242266, 2023). "In mice with CKD, intestinal Cyp24a1 deletion decreased PTH and FGF23 without precipitating hypercalcemia." (PMID 39688907, 2024). "In opposition native vitamin D is unlikely to cause hypercalcemia, as 1-hydroxylase activation is regulated by PTH, FGF-23, 24–hydroxylase." (PMID 38397979, 2024). "In T-PTX VDR +/+ and VDR−/− mice with constant PTH levels, hypercalcemia induced an increase in FGF23 levels, but to a lower extent in animals lacking VDR." (PMID 35807756, 2022). "As serum 1.25(OH)2D is high and FGF23 and PTH are reduced in such cases, secondary hypercalcemia and medullary calcinosis together with urolithiasis may be expected." (PMID 31514490, 2020). "The hypercalcemia suppresses PTH release and thus abrogates the stimulatory effect of PTH on FGF23." (PMID 29483574, 2018). "Nevertheless, this was not in line with the observed hypercalcemia, elevated levels of FGF23 and increase in 1,25-dihydroxy vitamin D3, which all should have suppress PTH level." (PMID 26566277, 2015). "It has been noted that fibroblast growth factor-23 (FGF-23), which may also stimulate CYP24 hydroxylase so as to avoid hypercalcaemia, is increased in response to a high dose of ergocalciferol." (PMID 24058907, 2013). "The simultaneous elevation of FGF-23 and PTH may decrease serum phosphorus levels, thereby protecting against ectopic calcification and tissue damage by reducing the calcium-phosphate product in the presence of hypercalcemia." (PMID 41509939, 2025). "Subsequently, the low levels of serum phosphate and FGF23 induce increases in CYP27B1 expression and 1a-hydroxylase activity; while inhibiting CYP24A1 expression and 24-hydroxylase activity, which have the combined effect of increasing 1,25-(OH)2D3 and hypercalcaemia." (PMID 33990852, 2022).
osteoporosis (58 papers, 2009 to 2026). A condition of reduced bone mass, with decreased cortical thickness and a decrease in the number and size of the trabeculae of cancellous bone (but normal chemical composition), resulting in increased fracture incidence. "FGF23‐deficient mice experience premature ageing, as evidenced by visible atherosclerosis, bone loss, osteoporosis, soft tissue calcification, emphysema, hypogonadism and generalized organ atrophy." (PMID 39054573, 2024). "At paracrine level, a connection between FGF23 and some bone remodeling abnormalities, such as Wnt1 mutations leading to early-onset osteoporosis and increasing fracture risk, has been suggested." (PMID 38634076, 2024). "In this representation of all the SLICC items, proteinuria ≥3.5 g/24 h (n = 7), arthritis (n = 40), and osteoporosis (n = 23) were significantly associated with higher levels of FGF23." (PMID 37627287, 2023). "The large cohort of males with osteoporosis revealed only a weak association between FGF23 and bone mineral density (BMD) that diminished when adjusting for potential confounders, including, age, height, weight, and smoking." (PMID 35269640, 2022). "Over the last ten years, the association between fibroblast growth factor 23 (FGF23) and osteoporosis has been studied." (PMID 35269640, 2022). "Meanwhile, FGF21 (r = -0.136, P < 0.05) and FGF23 (r = -0.151, P < 0.05) were both negatively associated with osteoporosis." (PMID 34011291, 2021). "Previous MR studies have mainly focused on the associations of genetically predicted FGF23 with bone-related phenotypes, which showed that FGF23 is inversely related to bone mineral density and osteoporosis." (PMID 34367258, 2021). "Many factors, such as secondary hyperparathyroidism, vitamin D deficiency, increased FGF23, and metabolic acidosis, are involved in the pathophysiology of subsequent osteoporosis in patients with CKD." (PMID 34011291, 2021). "PTH and FGF-23 promote bone resorption and reduce bone mineralisation, respectively, and are both implicated in osteoporosis." (PMID 32185580, 2020). "Dysregulation of FGF23 has been implicated in various bone disorders, including osteoporosis." (PMID 39062088, 2024). "Moreover, in an osteoporosis mouse model, FGF23 contributed to bone loss by activating the JAK/STAT pathway." (PMID 36831188, 2023). "However, when the SLICC-DI index items and domains were analyzed separately, apart from proteinuria ≥3.5 gm/24 h, only the musculoskeletal domain, encompassing arthritis and osteoporosis, was significantly associated with higher serum levels of FGF23." (PMID 37627287, 2023). "The proposed method infers that calcitriol can bind FGF23, which may be one of the causes of osteoporosis." (PMID 31194807, 2019). "The aim of this study is to investigate the potential role of circulating sRAGE in osteoporosis, in particular evaluating the correlation of sRAGE with the fracture risk, in association with bone mineral density, the fracture risk marker FGF23, and lipid metabolism." (PMID 28630637, 2017). "Osteoporosis alone is associated with fibroblast growth factor (FGF)-23, which may influence the level of phosphate." (PMID 25033287, 2014). "1,25-dihydroxyvitamin D3 (1,25D3) was reported to induce premature organismal aging in fibroblast growth factor-23 (Fgf23) and klotho deficient mice, which is of main interest as 1,25D3 supplementation of its precursor cholecalciferol is used in basic osteoporosis treatment." (PMID 22242193, 2012). "Currently, available evidence remains insufficient to support the use of serum FGF23 as a reliable marker in the evaluation of osteoporosis in the elderly." (PMID 41367909, 2025). "Other osteocyte-secreted factors have been reported to be elevated in monogenetic osteoporosis and renal osteodystrophy like FGF23 and DMP1." (PMID 39062269, 2024).